PRL (prolactin)
Diseases named in the same sentence as PRL in open-access papers (continued):
Sharing a sentence is not in itself a finding about the gene and the disease.
autoimmune disease (continued). "Increased prolactin production may contribute to the development and perpetuation of several autoimmune diseases, including Hashimoto’s thyroiditis, and may exert a negative impact on all aspects of female sexual functioning." (PMID 37375719, 2023). "The abnormal local PRL production by immune cells may explain the relationship between PRL and the onset of autoimmune disease." (PMID 36658300, 2023). "The correlation between PRL and autoimmune diseases such as systemic lupus erythematosus, rheumatoid arthritis, systemic sclerosis, and multiple sclerosis, has been confirmed, in which the excessive of PRL expression aggravates the symptoms of autoimmune diseases." (PMID 35910654, 2022). "More research is needed to determine the role of PRL in autoimmune disease because the mechanism(s) underlying this association are not fully understood, despite the extensive documentation of the PRL-mediated regulation of immune cells." (PMID 36389803, 2022). "The high expression of PRL may enhance the immune response of birds, but the continuous high expression may lead to the occurrence of autoimmune diseases in poultry." (PMID 35910654, 2022). "However, considering the increased PRL/cortisol ratio in some autoimmune diseases, it can be concluded that the observed decrease in PRL/cortisol ratio seems to favorably reduce the likelihood of autoimmune diseases in our study’s participants." (PMID 34305584, 2021). "Several evaluations confirmed the higher level of prolactin in patients with psoriasis; also, they reported the therapeutic effects of bromocriptine (antiprolactin secretion) on different autoimmune diseases including psoriasis, rheumatoid arthritis, and Reiter's syndrome." (PMID 34746311, 2021). "Patients from the same population presented an increase in serum PRL during 3 months of follow-up (0.5–4 mg/day); gender, pubertal status, risperidone dosage, psychiatry diagnosis, and personal/family history of autoimmune diseases also affected PRL elevation during treatment." (PMID 32373066, 2020). "It will be interesting to show whether PRL favors the presence of Treg IFNγ-secreting cells, especially because this has been reported for other autoimmune diseases." (PMID 26844452, 2016). "Generally lesswell known is that prolactin may also play a role in the activity of autoimmune diseases such as systemic lupus erythematosus and rheumatoid arthritis." (PMID 20184675, 2009). "Furthermore, PRL is involved in the immune system, autoimmune diseases, and the growth of different forms of cancer." (PMID 18713476, 2008). "Moreover, overexpression of PRL was indicated in various autoimmune diseases." (PMID 41476991, 2025). "Some hormonal abnormalities may be related to the exacerbation of autoimmune disease, as is the case for estrogen, PRL and probably GH, which are fundamental for the progression and severity of these pathological processes, while testosterone and P4 may have protective effects." (PMID 38680484, 2024). "Therefore, in this review, we describe the role of prolactin (PRL), estrogens, growth hormone (GH), testosterone and progesterone (P4) in the development and activation of B cells as well as their role in pathological processes such as autoimmune diseases." (PMID 38680484, 2024). "Even though PRL is described as immunostimulatory or -protective, there is evidence that PRL is immunosuppressive at higher concentrations and that inappropriate prolongation of PRL synthesis could lead to autoimmune diseases." (PMID 35847789, 2022). "Conversely, as PRL levels reportedly increase in patients with autoimmune diseases, and considering the known association between endometriosis and autoimmune diseases, a potential impact of endometriosis on serum circulating PRL, rather than of PRL on endometriosis, cannot be excluded." (PMID 33162942, 2020).
autoimmune disease (continued). "Prolactin's role in human autoimmune diseases remains a largely unexplored area in which research is greatly needed, particularly when investigating whether its involvement in different ethnic groups may cause different biological outcomes based on an individual's exposure and lifestyle factors." (PMID 26583155, 2015). "These analyses were conducted to illustrate that PRL is not only an endocrine hormone but also an immune factor, thereby providing evidence that GLM is an autoimmune disease." (PMID 40948778, 2025). "Other chronic conditions including autoimmune diseases such as systemic lupus erythematosus, antiphospholipid syndrome, rheumatoid arthritis, multiple sclerosis, systemic sclerosis, autoimmune thyroid disease, and coeliac disease may also reduce prolactin production." (PMID 38829475, 2024). "Age, gender, ethnicity, cancer type, ICI types and duration of use, pre-existing autoimmune diseases, low prolactin and number of hormone axis affected were not shown to be associated with hormonal recovery." (PMID 33890870, 2021). "Although not fully demonstrated, prolactin has already been discussed as a potential player in certain autoimmune diseases such as lupus." (PMID 32235676, 2020). "Prolactin's exact role in the physiology and pathogenesis of autoimmune diseases, such as lupus, has not been totally clarified." (PMID 26583155, 2015). "Certainly, this speculation, although undoubtedly interesting, is based on the role of prolactin in other autoimmune diseases, whilst not in polymyositis." (PMID 25431724, 2014). "Prospective studies are required to definitively answer the question of whether PRL plays a role in the pathogenesis of pemphigus vulgaris given that PRL does play a role in other autoimmune diseases, at least partially via inhibition of negative selection of autoreactive B cells." (PMID 39000207, 2024). "Since OLP is an autoimmune disease and also there is no evaluation in literature about the relation of sexual hormone on clinical aspect of OLP presentation, in this study, we aimed to evaluate any possible relation of FSH, LH, and prolactin level and OLP." (PMID 34746311, 2021).
erectile dysfunction (49 papers, 1998 to 2026). Persistent or recurrent inability to achieve or to maintain an erection during sexual activity. "Erectile dysfunction and ejaculation difficulties are side effects unique to men, and antipsychotics—especially those raising prolactin or with alpha-adrenergic blocking properties—can cause impotence in a substantial fraction of men with SZ." (PMID 40589655, 2025). "study, which examined the association of hypoPRLemia with sexual dysfunction and showed that a higher risk of erectile dysfunction and premature ejaculation was found in patients with lower PRL levels." (PMID 38370355, 2024). "Prolactin levels seem to have a prognostic role of future CVD events in men with erectile dysfunction and was associated with all-cause and CVD mortality in the general population, as well as in patients with chronic kidney disease." (PMID 33396861, 2020). "Furthermore, erectile dysfunction in association with high prolactin levels is frequent in patients suffering from psychiatric disorders and taking psychotropic drugs." (PMID 35366160, 2022). "Finally, prolactin provides the body with sexual gratification after sexual acts, although high blood levels of prolactin are likely to produce impotence and loss of libido." (PMID 31568703, 2019). "Prolactin plays a key role in the regulation of sexual behaviour and activity, and elevated serum prolactin levels associated with antipsychotic medication are known to cause erectile dysfunction, orgasmic difficulties, amenorrhoea and gynaecomastia." (PMID 19102734, 2008). "Despite similar PRL concentrations, menstrual disorders are the most common sign in women, whereas in men: erectile dysfunction and decreased libido." (PMID 38370355, 2024). "The authors indicated that other than age and general PANSS score, prolactin levels in the blood also predicted erectile dysfunctions in males." (PMID 34777053, 2021). "Erectile dysfunction (ED) is strongly correlated with sex-hormones and prolactin levels, and has been used as a proxy of quality of life." (PMID 33396861, 2020). "Reduction of FSH levels by excessive prolactin secretion also gives rise to hypoactive sexual desire and erectile dysfunction." (PMID 29515515, 2018). "Prolactin’s function in men, however, is not well understood, although excessive prolactin release can lead to reduced sex drive (i.e., libido) and impotence." (PMID 15706790, 1998). "A study evaluated the possible role of changes in hormone levels in the onset of erectile dysfunction in patients with CP/CPPS without demonstrating correlations with testosterone levels, while only prolactin levels were shown to be inversely correlated with the severity of erectile dysfunction." (PMID 40218236, 2025). "Due to absent libido and impotence, testosterone enanthate was administered after 12 weeks, and was associated with a marked increase in prolactin levels and an increase in tumor size." (PMID 36835974, 2023). "Erectile dysfunction has been explored as a condition secondary to elevated prolactin; however, the mechanisms by which elevated prolactin levels cause erectile dysfunction have not yet been clearly established." (PMID 25844161, 2015). "Hypogonadism, characterized by decreased libido, erectile dysfunction (ED), gynecomastia, is a primary symptom of HPRL in men, and typically manifests with elevated serum prolactin (PRL) levels, suppressed gonadotropin levels, and low testosterone levels." (PMID 40966237, 2025). "On the other hand, the evaluation of other markers, such as FSH, LH, prolactin, SHBG, and estradiol, is typically unnecessary in the routine work-up of erectile dysfunction, as elevated levels of these hormones are infrequent and have minimal impact on erectile function." (PMID 39941224, 2025). "In contrast, LH, estradiol, SHBG, and prolactin do not demonstrate any statistical correlation with erectile dysfunction and should not be recommended as routine investigations." (PMID 39941224, 2025).
erectile dysfunction (continued). "The infrequent occurrence and minimal impact of elevated FSH, LH, prolactin, SHBG, or estradiol levels in cases of erectile dysfunction do not support their routine evaluation." (PMID 39941224, 2025). "Although LH, PRL, and SHBG showed increases in median values across each severity group of erectile dysfunction, and estradiol demonstrated decreases, these changes did not statistically correlate with the severity of erectile dysfunction." (PMID 39941224, 2025).
Microprolactinoma (49 papers, 2009 to 2025). A pituitary prolactin cell adenoma of less than 10 mm diameter. "This is plausible even in patients with microprolactinomas, as those with high baseline PRL levels were associated with a poor treatment response to DAs in the long term." (PMID 39904877, 2025). "Two women (32 and 36 years old) with chronic hPRL-HA (prolactin: between 94 and 102 and 98 and 112 ng/mL, respectively) caused by cabergoline-resistant microprolactinomas." (PMID 29264460, 2017). "However, the PRL values up to 2000 mlU/L may be due other pharmacotherapy, oestrogens, functional causes, or microprolactinomas, while macroadenomas are associated with concentrations over 5000 mlU/L." (PMID 33380894, 2021). "Hypogonadism improved after PRL normalization in 5 out 6 patients with microprolactinoma and 28 out 33 patients with macroprolactinoma." (PMID 39900728, 2025). "The debate continues regarding the expansion of first-line surgical indications for prolactin-producing tumors, particularly in patients with microprolactinomas, which offer a promising opportunity to reduce reliance on DAs." (PMID 39904877, 2025). "iii)Patients with microprolactinomas who have PRL values of > 290 μg/L are likely to require long-term supplemental DA therapy." (PMID 39904877, 2025). "In conclusion, we found that 89.4% of men with microprolactinoma achieved normal prolactin levels with cabergoline treatment." (PMID 40199840, 2025). "It contrasts with the belief that cystic prolactinomas secrete less prolactin owing to reduced cellular content and that solid macroprolactinomas are larger than cystic or solid microprolactinomas." (PMID 41199869, 2025). "Serum prolactin levels in macroprolactinomas (maximum tumor diameter, ≥1cm) usually exceed 250ng/mL, whereas those in microprolactinomas frequently range from 100 to 200ng/mL." (PMID 40960781, 2025). "The risk of symptomatic growth of prolactinomas during pregnancy is related to the size of the tumor, length of previous treatment and higher PRL levels, and is less than 5% in microprolactinomas." (PMID 38765515, 2024). "The prolactin levels in patients with microprolactinomas (n = 121) ranged from 51 to 525 ng/mL (mean, 196.04 ± 97.86 ng/mL; median, 181 ng/mL)." (PMID 39420933, 2024). "Macroadenomas (tumor size > 10 mm) often exhibit serum PRL higher than 250 μg/L, while microprolactinomas (tumor size < 10 mm) commonly result in hyperprolactinemia with the range between 100 and 200 μg/L." (PMID 38375408, 2024). "The mean prolactin levels in patients with macroprolactinemia were lower than those observed in patients with microprolactinomas (p < 0.01), idiopathic macroprolactinemia (p < 0.01), or macroprolactinomas (p < 0.001)." (PMID 39420933, 2024). "At baseline, macroprolactinoma patients had lower testosterone levels (p=0.005) and higher prolactin levels (p<0.001) compared to those with microprolactinoma." (PMID 38645431, 2024). "Within these limitations, review of studies published between 2000 and 2015 has shown that transsphenoidal surgery leads to normoprolactinemia in 71–100% of microprolactinomas (with prolactin checked shortly after or within the first weeks following surgery)." (PMID 36928728, 2023). "DA normalize prolactin (PRL) levels in more than 90% of people with microprolactinomas and in 77% of people with macroprolactinomas, and reduce tumor size in up to 89% of cases." (PMID 36927797, 2023). "Currently, given the physiologic decline in PRL levels occurring with menopause, DAs treatment can be withdrawn in asymptomatic women with microprolactinoma considering that tumor enlargement rarely occurs." (PMID 36237192, 2022). "Among the 21 women of the PCOS/hPRL cohort, 5 (23.8%) had a microprolactinoma and all of them had PRL level ≥ 60 ng/ml." (PMID 35250884, 2022). "The role of surgical intervention should be re-evaluated in the management of treatment-naive microprolactinoma patients, particularly those with PRL level of ≤200 ng/mL." (PMID 34504526, 2021).
Microprolactinoma (continued). "Surgery showed a high remission rate after treatment withdrawal (DA withdrawal in the medical group; no other therapy was applied after surgery in the surgical group) in microprolactinomas, particularly in patients with a preoperative PRL level of ≤200 ng/mL." (PMID 34504526, 2021). "We additionally found that microprolactinoma patients with a preoperative PRL level of ≤200 ng/mL had a significantly higher rate of biochemical remission than those with a level of >200 ng/mL, in accordance with previous reports." (PMID 34504526, 2021). "Postoperative PRL values remained significantly higher in patients with macroprolactinomas than in those with microprolactinomas (p = 0.03)." (PMID 33847973, 2021). "Regular monitoring of the serum prolactin level every 6–12 months is recommended over immediate treatment initiation in asymptomatic patients with microprolactinomas." (PMID 33946142, 2021). "When stratified for tumor size, elevated prolactin levels were a significant determinant of healthcare utilization only in microprolactinoma patients (OR 6.318, 95% CI 1.429; 27.934)." (PMID 33025546, 2021). "The macroprolactinoma group with a higher PRL level at diagnosis (P = 0.039) showed a remarkable decrease in the serum PRL level after the TSA (P = 0.014) as compared with the findings in the microprolactinoma group." (PMID 32849307, 2020). "In general, prolactin levels are related to tumor size: microprolactinomas have lower prolactin concentrations than macroprolactinomas." (PMID 30542321, 2018). "Another study also showed that cabergoline has a greater effect than bromocriptine in normalizing prolactin concentration and decreasing tumor size after 24 months of treatment, both in macro- and microprolactinomas." (PMID 30542321, 2018). "Microprolactinomas exhibit relatively low secretion of PRL and better prognosis while macroprolactinomas are more often associated with particular difficulties in management due to their high secretion of PRL and aggressive biological behaviors." (PMID 30410470, 2018). "From this perspective, we have reasons to consider, between medication and surgery, which is the optimal choice for prolactinomas, particularly for patients with microprolactinomas and low PRL level." (PMID 30410470, 2018). "In this regard, it is reasonable for experienced and handy neurosurgeon to recommend surgical management as primary option to achieve better long-term prognosis, especially in patients with microprolactinomas or low preoperative PRL level." (PMID 30410470, 2018). "In our study, patients with microprolactinomas and residual macroprolactinomas were treated with similar doses of DA and had the same PRL measurements after 2 years of treatment." (PMID 25737721, 2015). "The expected success rate for normalizing PRL post-operatively is 65–85 % for microprolactinomas but less than 40 % for macroprolactinomas." (PMID 28702224, 2015). "In the macroprolactinoma group, PRL levels three months postoperatively were similar to the initial PRL levels of microprolactinomas (83.3 mcg/L (50.0–157.6) versus 63.5 (48.3–93.0), P = 0.275)." (PMID 25737721, 2015). "Comparable remission rates and prolactin levels were reached in microprolactinomas and residual macroprolactinomas using similar doses of dopamine agonists." (PMID 25737721, 2015). "It was notable that, in the CD + PRL group, the normalization rate for patients with macroprolactinomas was significantly lower than that for patients with microprolactinomas." (PMID 25506361, 2014). "Another study reported high prolactin levels during migraine attack, but the study was carried on subjects who had microprolactinomas." (PMID 21331754, 2011). "Prolactin at different intervals and only one female was later found with microprolactinoma (prolactinemia over 150 ng/ml, outside the pregnancy or medication/other medical condition known to raise prolactine levels)." (PMID 20108497, 2009).